ASS1 (argininosuccinate synthase 1)
Diseases named in the same sentence as ASS1 in open-access papers (continued):
Sharing a sentence is not in itself a finding about the gene and the disease.
cancer (continued). "Some other conditions like hypoxia and enhanced glutaminolysis may induce ASS1 expression in ASS1-ve cancer cells." (PMID 28750681, 2017). "ADI and BCT-100 were pre-clinically and clinically proven to inhibit arginine auxotrophic tumors with ADI targeting ASS1 deficient cancers and BCT-100 targeting ASS1 and/or OTC negative cancers." (PMID 28464918, 2017). "Reduced ASS1 expression is frequently detected in various human cancers including sarcomas." (PMID 27683125, 2016). "The moderate anticancer effect of arginine deprivation in clinical trials has been linked to an induced argininosuccinate synthetase (ASS1) expression in initially ASS1-negative tumors, and ASS1-positive cancers are anticipated as non-responders." (PMID 27689335, 2016). "Therefore, the correlationbetween metastatic/migration potential and Ass1 expression in these murinegastric cancer cell lines further support an important role of Ass1 in mediatingmetastasis." (PMID 25928182, 2015). "Extending beyond HCC to other cancers, our results suggest that in the combination setting, a patient does not necessarily need to have an ASS1-deficient tumor to reap benefit from an ADI-PEG 20 and cisplatin drug treatment." (PMID 25164070, 2014). "Additionally, incorporating ASS1 immunohistochemical staining into pre-neoadjuvant biopsy assessments should be considered to optimize neoadjuvant treatment strategies and advance the implementation of personalized cancer therapy." (PMID 41300990, 2025). "The decreased nucleotide synthesis and prolonged G1 phase in cancer cells with ASS1 deficiency, even without induction of DNA damage, suggests that ASS1 loss may delay entrance to the cell cycle by dysregulating nucleotide synthesis even at a basal state." (PMID 38858597, 2024). "Thus, ASS1 downregulation may further contribute to error-prone mutagenesis, increasing cancer adaptability potential and survival." (PMID 38858597, 2024). "Finally, this review discusses how the identification of biomarkers that may denote enhanced sensitivity to ADI-PEG20 beyond ASS1 may be realized in future clinical practice, thus personalising arginine deprivation therapy for patients with cancer." (PMID 36903394, 2023). "Finally, we review approaches to target ASS1 for cancer therapies." (PMID 35910381, 2022). "However, little is known about the cancer-promoting mechanisms fostered by the reduction of ASS1." (PMID 35864952, 2022). "Given that ASS1 is commonly downregulated in multiple tumor types and participates in the regulation of tumor development depending on diverse mechanisms, it may be a robust potential therapeutic target for cancer management." (PMID 35910381, 2022). "Neither ASS1 nor ARG2 expression by cancer cells was linked with TIL-score or PD-L1 expression." (PMID 34344457, 2021). "The most marked cancer-related difference seems to be associated with ODC and ARG2 expression patterns, mostly changed from very strong to strong (with DDAHs) or moderate (with PRMTs), and with loosening of ASS1 and ASL association with each other as well as other pathway enzymes." (PMID 34439753, 2021). "Moreover, ASS1 expressing cancer cells may take up less arginine from the stroma, leaving larger amounts of arginine available to TILs." (PMID 34344457, 2021). "The role of ASS1 in tumor biology is unclear, as the protein may act either as a tumor suppressor or as pro-metastatic or carcinogenic factor in various carcinomas." (PMID 33838671, 2021). "There was either no or very low ASS1 expression in cancer associated fibroblasts in all cases." (PMID 28187218, 2017). "Similarly, ASS1 expression is greatly variable in human malignant tumors." (PMID 28187218, 2017).
cancer (continued). "This study is the first to report the role of EI24 in promoting cancer survival via translational regulation of the metabolic enzyme ASS1, thus paving a route for further investigation into the link between EI24 and cancer metabolism." (PMID 40253325, 2025). "The de novo biosynthesis of arginine, catalyzed by the enzymes argininosuccinate synthetase 1 (ASS1) and argininosuccinate lyase (ASL), is frequently dysregulated in cancer." (PMID 40535116, 2025). "Moreover, the addition of citrulline could restore the levels of total and phosphorylated STAT1 and PSMB9 proteins in response to IFNγ in ASS1-expressing cancer cells grown in an arginine-depleted medium, confirming the essentiality of arginine for the cancer cell response to IFNγ." (PMID 41511309, 2025). "Conversely, ASS1 is significantly overexpressed in various cancers, including CRC, where it functions as an oncogenic factor promoting both cancer cell proliferation and metastasis." (PMID 41304979, 2025). "Argininosuccinate synthase (ASS1), a critical enzyme in the urea cycle, acts as a tumor suppressor in many cancers." (PMID 38710705, 2024). "ASS1 knockout or knockdown enhanced PHGDH protein stabilization to increase serine synthesis and promote cancer cell proliferation and, consequently tumorigenesis, providing a novel anticancer mechanism of ASS1 in TNBC." (PMID 38710705, 2024). "Among the non-immune cells, apart from a small population of tumor-associated endothelial cells (21 cells, 0.07% of the total cells, marked with VWF and ENG), the rest were cancer cells (11,228 cells, 35.46% of the total cells, marked with GPC3 and ASS1)." (PMID 38169544, 2024). "As a kind of novel marker for malignant tumors, lncRNAs can modulate metabolism-related genes (c-MYC, ASS1, mTORC1), and further exert complex impacts on tumor progression, which expands our understanding of cancer metabolism." (PMID 36969848, 2023). "According to recent evidence, argininosuccinate synthase 1 (ASS1) is a crucial enzyme for limiting aspartate metabolism and has a reduced expression level as a tumor suppressor in cancer cells." (PMID 37161350, 2023). "Furthermore, arginine cannot be metabolized in cancer cells due to loss of function of argininosuccinate synthase 1; therefore, arginine may be accumulated in cancer cells without being used." (PMID 37686644, 2023). "Reduced expression of key urea cycle enzymes including ASS1, ASL and ARG2 has been reported in a number of cancer types, suggesting tumor suppressive roles of these urea cycle enzymes." (PMID 34068137, 2021). "Proinflammatory cytokines tumor necrosis factor (TNF)-α and IL-1β regulate ASS1 in cancer cell lines, and TNF-α has been observed to co-localize with ASS1 in epithelial ovarian cancer." (PMID 32266129, 2020). "In support of this, argininosuccinate synthase (ASS1), which catalyzes the penultimate step in the synthesis of arginine and is involved in the urea cycle, is frequently silenced in multiple cancers." (PMID 32722390, 2020). "Argininosuccinate is an intermediate of the urea cycle produced by argininosuccinate synthetase 1 (ASS1) from citrulline and aspartate and was found to be decreased in several cancer cell lines when cultured in a physiological culture medium." (PMID 30613774, 2019). "Defective arginine synthesis, due to the silencing of argininosuccinate synthase 1 (ASS1), is a common metabolic vulnerability in cancer, known as arginine auxotrophy." (PMID 30393775, 2018). "Aberrant expression of argininosuccinate synthetase (ASS1, also known as ASS) has been found in cancer cells and is involved in the carcinogenesis of gastric cancer." (PMID 25333458, 2015). "A strong correlation between the methylation of the ASS1 promoter and sensitivity to ADI-PEG 20 has been established in these various cancer cell lines." (PMID 25164070, 2014). "The two specific luminal B candidates, ASS1 and ZFP36L2 downregulated in relation with DNA methylation have been reported targeted in cancers." (PMID 24416132, 2014).
cancer (continued). "Without the expression of ASS1, cancer cells become auxotrophic for arginine, resulting in a dependence on extracellular arginine sources for survival." (PMID 39898973, 2025). "Nevertheless, EI24 substantially prolonged cancer cell survival upon arginine deprivation by enhancing ASS1 in these cell lines, but not ASS1-efficient cells." (PMID 40253325, 2025). "Following induction of DNA damage by Dox, SMARCC1 immunoprecipitation of the chromatin-bound fraction in cancer cells without ASS1 demonstrated decreased levels of SMARCC1 protein and lower levels of succinated SMARCC1." (PMID 38858597, 2024). "Cancer cells lacking ASS1 and/or other arginine lyase enzymes are generally considered arginine auxotrophic tumors." (PMID 39462426, 2024). "The ASS1 and OTC negativity could also serve as predictive biomarkers for the response in other arginine-dependent cancers." (PMID 39570001, 2024). "To evaluate the increased requirement for fumarate following DNA damage, we incubated nuclei isolated from cancer cells with and without ASS1 with isotopically labeled 13C4-aspartate." (PMID 38858597, 2024). "ASS1 is a rate-limiting enzyme in the arginine synthesis pathway, which is severely reduced or absent in some types of aggressive cancers, thus exhibiting exogenous arginine dependence." (PMID 37127605, 2023). "And the arginine metabolism in cancers is totally reshaped because of the lack of ASS1, a key enzyme during the production of arginine." (PMID 37214463, 2023). "Cancer cells were unable to synthesize arginine from citrulline without ASS1, and were dependent on exogenous arginine." (PMID 36798123, 2023). "To explore whether the relationship between ASS1 and BAP1 was a general feature of cancer, we examined TCGA pan-cancer datasets." (PMID 36669126, 2023). "The argininosuccinate synthetase 1 (ASS1), which makes cancer cells dependent on exogenous supply, may be used for targeted therapy for arginine auxotrophic cancers." (PMID 36362209, 2022). "Due to the low or non-expression of essential enzymes in arginine endogenous synthesis, especially ASS1, ASL, and OCT, in numerous cancers, tumor cells cannot ordinarily generate endogenous arginine and are highly dependent on exogenous arginine; these tumors are referred to as arginine-auxotrophic." (PMID 35814439, 2022). "On the other hand, defective l-arginine synthesis, due to the silencing of argininosuccinate synthase 1 (ASS1), is a common metabolic weakness in cancer and results in an intrinsic dependence on extracellular l-arginine due to an inability to synthesise l-arginine for growth." (PMID 36010962, 2022). "Moreover, ASS1 and ASL are downregulated in cancer cells, resulting in the inability to synthesize endogenous arginine, which makes cancer cells more dependent on the extracellular arginine pool." (PMID 35898872, 2022). "We propose that ASS1 and CPS1 might be necessary for hepatocellular tumorigenesis and early-stage cancer to detoxify, but reduce in the advanced stage when tumor cells are faced with hostile microenvironment." (PMID 35655758, 2022). "As a result, arginine deprivation has emerged as an attractive therapy in cancers lacking ASS1 (and ASL)." (PMID 34861885, 2021). "ARG2 and ASS1 enzymes are extensively expressed in NSCLC stroma and cancer cells, respectively." (PMID 34344457, 2021). "Patients with ASS1 expression by cancer cells had a better prognosis especially when CAFs did not express ARG2 (p = 0.004)." (PMID 34344457, 2021). "Silencing of ASS1 and/or ASNS may provide a selective advantage for cancer cells, allowing for diversion of aspartate towards other anabolic pathways such as nucleotide biosynthesis." (PMID 33669382, 2021). "Auxotrophic tumors with lack of ASS1 expression by cancer cells are expected to require exogenous supplies of Arg." (PMID 34344457, 2021).
cancer (continued). "Bivariate stratification, however, showed that patients with ASS1 expression by cancer cells had a better prognosis especially when CAFs did not express ARG2 (p = 0.004)." (PMID 34344457, 2021). "As most arginine is made and exported from the kidney cells for utilization by other cell types, many cancers take advantage of this extracellular supply by silencing ASS1 expression without compromising their arginine supply." (PMID 33478587, 2021). "Analysis according to the microvessel density (MVD) showed that tumors that did not express ASS1 in cancer cells had a significantly higher MVD in the tumor invading front (p < 0.02)." (PMID 34344457, 2021). "Treatment of NEI-01 specifically inhibited cell viability of MIA PaCa-2 and PANC-1 cancer cell lines, which were ASS1 negative." (PMID 32353864, 2020). "The results demonstrated that NEI-01 inhibited cell viability of ASS1-negative cancer cell lines (e.g. MIA PaCa-2, PANC1)." (PMID 32353864, 2020). "Those cancer cells do not express argininosuccinate synthetase 1 (ASS1), which is essential for endogenous arginine synthesis." (PMID 29805774, 2018). "As expected in ASS1-high cancer cell lines that are not sensitive to ADI-PEG 20 the combination treatment had the same effect as rhTRAIL alone (data not shown)." (PMID 30651925, 2018). "Arginine deprivation can inhibit the growth of arginine auxotrophic cancers lacking key enzymes, such as argininosuccinate synthase (ASS1), that normal cells use to produce arginine from citrulline." (PMID 30651925, 2018). "The other nutrient, arginine, is regarded as an essential amino acid for cancer cells that do not express or express very low levels of argininosuccinate synthase 1 (ASS1), a key enzyme to synthesize arginine from citrulline." (PMID 28629173, 2017). "Of note, LY6D, ST3GAL4, ASS1, PTP4A3 (also named PRL-3), UBE2C (also named UBCH10), and E2F3 are novel oncogenes and biomarkers whose overexpression are related to metastases, migration, or proliferation of NSCLC and other cancers." (PMID 27935865, 2017). "Our experimental series further substantiated that the capacity of cancer cells to utilize citrulline for growth induction in the absence of arginine depends not only on ASS1 protein level but also on citrulline availability." (PMID 27689335, 2016). "Epigenetic silencing via promoter CpG methylation in cell lines lacking ASS1 expression has been demonstrated in multiple cancer types." (PMID 25164070, 2014). "Interestingly, there are even cancer cell lines that rather than repress ASS1, upregulate ASS1 expression." (PMID 39920310, 2025). "However, some arginine-auxotrophic cancer cells cannot autonomously synthesize arginine due to lacking of argininosuccinate synthetase 1 (ASS1) or ornithine transcarbamylase (OTC)." (PMID 41460862, 2025). "We also identified the top 1 GEAR in individual cancer types, such as TLL1 (BLCA), PGK1 (BRCA), RFXANK (CESC), DPP7 (COAD), VWA8 (KIRC), SCMH1 (LGG), HILPDA (LIHC), TLE1 (LUAD), CD151 (LUSC), ANKRD13A (OV), SOCS2 (PAAD), DRG2 (PRAD), ADAMTS6 (STAD), PSMB8 (THCA), ASS1 (UCEC)." (PMID 41404730, 2025). "Indeed, we found that although adding fumarate did not alter the survival of cells expressing ASS1 following DNA damage, it decreased apoptosis and rescued survival in cancer cells with ASS1-KO." (PMID 38858597, 2024). "However, the fact that adding pyrimidine only partially restored cell viability indicates the possibility of an alternative antitumor pathway involving ASS1, and the signaling pathways and interacting proteins of ASS1 in cancer have not been fully elucidated." (PMID 38710705, 2024). "Lacking ASS1 may promote the proliferation of these cancer cells by the conversion of aspartate to pyrimidine synthesis." (PMID 36978187, 2023). "Further research is required to elucidate whether this metabolic relationship exists in the context of other ASS1-negative cancers and stromal cells." (PMID 37010783, 2023).
cancer (continued). "The lack of ASS1 change in HLCS knockdown MCF-7 cells may recapitulate the early stage of cancer, where ASS1 may not be essential during early stage of tumor progression." (PMID 38283944, 2023). "ASS1 also plays a non-metabolic role by suppressing Akt signaling and attenuating cancer growth." (PMID 38283944, 2023). "However, it had limitations such as it is only effective on cancer cells lacking the ASS1 enzyme, it has low serum half-life, and it is highly immunogenic." (PMID 32390765, 2020). "Here, we deepened the study on nine of them (ASS1, EIF4G1, GALNT7, GLUT1, IGF2BP3 (IMP3), ITGA4, RAN, SOD1, and THBS2) to ascertain whether they are truly mesothelial cancer driver genes (CDGs) or genes overexpressed in an adaptive response to the tumoral progression (“passenger genes”)." (PMID 32659970, 2020). "Indeed, the activity of the key enzymes involved in NO production, namely ASS1, ASL, arginase and NOS, are frequently altered in various types of cancers, enabling us to identify vulnerabilities in NO-related pathways and to design novel anti-cancer drugs that target these enzymes." (PMID 30082427, 2018). "We hypothesized that FH-deficient cells may be auxotrophic for arginine, a phenomenon often observed in ASS1-negative cancers." (PMID 23643539, 2013). "Arginine depletion therapy with ASS1 inhibition could have a role in the treatment of tumors proficient for arginine synthesis (extensive expression of ASS1 by cancer cells), provided that the tumor stroma does not already play this role by ARG2 overexpression." (PMID 34344457, 2021). "Indeed, independent of arginine importance, cancer cells become more proliferative when ASS1 is silenced because of the increased cytosolic availability of its substrate, aspartate, for pyrimidine synthesis by CAD (carbamoyl-phosphate synthase 2, aspartate transcarbamylase and dihydroorotase)." (PMID 30082427, 2018). "Levels of the rate-limiting enzyme for arginine biosynthesis, argininosuccinate synthase 1 (ASS1), are severely reduced or absent in some aggressive and chemoresistant cancers." (PMID 35736499, 2022). "ASS1 and ARG2 expression by cancer cells or by CAFs were not related to the expression of HIF1α, LDH5, or CA9 by cancer cells." (PMID 34344457, 2021). "Just as ADI-PEG20 is against tumors without ASS1 expression, rhArg1-PEG shows its anti-tumor effect on cancer cells with negative expression of OTC." (PMID 34299249, 2021).